EPHA3 (EPH receptor A3)
Diseases named in the same sentence as EPHA3 in open-access papers (continued):
Sharing a sentence is not in itself a finding about the gene and the disease.
colon cancer (5 papers, 2016 to 2023). "The effects of EPHA3 on the growth of colon cancer cells were further investigated using a xenograft model." (PMID 28169277, 2017). "Our results indicate that restauration of EPHA3 expression in colon cancer cells with low/undetectable EPHA3 levels, or EphA3 deletion in mouse models of intestinal tumorigenesis, does not alter the phenotype of these tumor cells." (PMID 28169277, 2017). "Collectively, these results show that the reintroduction of EPHA3 into deficient colon cancer cells does not affect their growth." (PMID 28169277, 2017). "Next, we investigated whether restoration of EPHA3 signaling affected the invasive potential of colon cancer cells." (PMID 28169277, 2017). "Here we used the cell line systems generated to study whether EPHA3 signaling regulates the proliferative activity of colon cancer cells." (PMID 28169277, 2017). "In addition, recent findings localized EphA3 predominantly to the stromal tumor microenvironment of lung, prostate, and colon cancers, and mouse tumor xenografts." (PMID 27494882, 2016). "However, we observed no changes in the motility or proliferation in these isogenic cell line systems, suggesting that in colon cancer cells EPHA3 mutations are not oncogenic." (PMID 28169277, 2017). "To investigate this possibility, we overexpressed mutant EPHA3D806N in DLD1 and LS174T colon cancer cells with low endogenous EPHA3 expression, or used a CRISPR/Cas9 strategy to knockout the mutant EPHA3 expressed at high levels in SW48 cells." (PMID 28169277, 2017). "Although our results with the EphA3 knockout mouse model indicate that the loss of EphA3 is not an important event in the early stages of tumor development, it remained possible that EPHA3 may be involved in the metastatic process of colon cancer cells." (PMID 28169277, 2017). "Despite the evidence from the genetic screens, we found that overexpression of wild type or mutant EPHA3 did not affect the growth of colon cancer cells." (PMID 28169277, 2017). "When considered together these results demonstrate that the reintroduction of EPHA3 in colon cancer cells does not interfere with their metastatic potential." (PMID 28169277, 2017). "We show here that ectopic expression of wild type EPHA3 in colon cancer cells did not affect their growth, motility/invasion or metastatic potential in vivo." (PMID 28169277, 2017). "Moreover, overexpression of mutant EPHA3 or deletion of the endogenous mutant EPHA3 in colon cancer cells did not affect their growth or motility." (PMID 28169277, 2017). "Moreover, reintroduction of EPHA3 in colon cancer cells did not change their motility/invasion in vitro or their metastatic potential in a mouse model of experimental metastasis." (PMID 28169277, 2017). "Moreover, ectopic expression of wild type EPHA3 did not affect the capacity of colon cancer cells to form colonies when growing on a solid or a semisolid soft-agar substrate." (PMID 28169277, 2017).
brain tumor (4 papers, 2016 to 2024). "Similar to primary samples we determined EphA3 to be broadly and robustly expressed across all CNS tumor models examined, including high and low grade brain tumors." (PMID 39111833, 2024). "We next sought to examine EphA3 cell surface antigen expression on brain tumor models by staining with a recombinant anti-EphA3 antibody with the same variable scaffold and CDRs of ifabotuzumab (WO2008/112192A2)." (PMID 39111833, 2024). "Analysis of the cell surfaceome in pediatric and adult tumors revealed EphA3 as a prominent cell surface protein across various brain tumor subtypes, especially in the context of comparison to existing immunotherapeutic targets in clinical development EphA2, HER2, CD276, CD70, and EGFR." (PMID 39111833, 2024). "We next analyzed specimens of primary brain tumors for the presence of EphA3." (PMID 27494882, 2016). "Collectively, these data clearly demonstrate that the EphA3 CAR expressed in primary human CD4+ and CD8+ T cells, whereby it can function in an antigen-dependent manner to signal to induce activation, cytokine secretion, and exert cytotoxic effect on target brain tumor cell lines." (PMID 39111833, 2024).
leukaemia (4 papers, 2015 to 2021). "Both the EphA2 mAb IF7 coupled to Lutetium-177 and then anti-EphA3 antibody IIIA4 linked to an α-particle-emitting Bismuth-213 payload showed therapeutic effect in EphA2 and EphA3 expressing leukemia models." (PMID 34926242, 2021). "EphA3 was found to be expressed in the preB leukaemia cell line and in a subset of samples from patients with leukaemia." (PMID 27766946, 2016). "Our focus—EphA3—is overexpressed in different types of human leukaemia, including T-ALL." (PMID 34359759, 2021). "Although no direct link was found between EphA3 expression and LSCs, studies have shown that anti-EphA3 may act against CSCs, since its incubation with preB leukaemia cells leads to the loss of the CSC’s in vitro ability to form colonies." (PMID 27766946, 2016). "The mice bearing 20–30% GFP+ MLL-AF9 leukemia were treated with 3 MBq/21 μg of Lu-IF7 mAb, unlabelled IF7 mAb, IIIA4 anti-EphA3 mAb (Lu-IIIA4) control (as MLL-AF9 leukemia do not express EphA3) or PBS control." (PMID 26083390, 2015).
pulmonary fibrosis (4 papers, 2021 to 2025). Chronic progressive interstitial lung disorder characterized by the replacement of the lung tissue by connective tissue, leading to progressive dyspnea, respiratory failure, or right heart failure. "For example, EphA3 expression is significantly increased in idiopathic pulmonary fibrosis and antibody-directed killing of EphA3+ cells ameliorated pulmonary fibrosis in humanized immunodeficient mice." (PMID 39164267, 2024). "Moreover, EPHA3+ lung cells from IPF patients induce lung fibrosis in mice, and antibody-mediated depletion of these cells ameliorates fibrosis." (PMID 41279897, 2025). "Notably, studies have demonstrated that the administration of anti-EPHA3 monoclonal antibodies in mice with idiopathic pulmonary fibrosis can prevent the progression of fibrosis." (PMID 40406118, 2025). "Targeting CCR10+EphA3+ cells ameliorated lung fibrosis in humanized NSG mice." (PMID 33945505, 2021). "Thus, human CCR10+ cells promote pulmonary fibrosis, and EphA3 mAb–directed elimination of these cells inhibits lung fibrosis." (PMID 33945505, 2021). "Ifabotuzumab-targeted killing of EphA3+ cells significantly reduced the numbers of CCR10+ cells and ameliorated pulmonary fibrosis in humanized NSG mice." (PMID 33945505, 2021).
small cell lung carcinoma (4 papers, 2016 to 2023). Small cell lung cancer (SCLC) is a highly aggressive malignant neoplasm, accounting for 10-15% of lung cancer cases, characterized byrapid growth, and early metastasis. "Recent studies have shown that EPHA3 is down-regulated in chemotherapy-resistant ovarian cancer cells and implicated in regulation of multidrug resistance in small cell lung cancer via the PI3K signaling pathway, which has been frequently linked to taxane resistance." (PMID 34055636, 2021). "Additionally, EPHA3 has been associated with the regulation of multi-drug resistance in small cell lung cancer via the PI3K/BMX/STAT3 signaling pathway." (PMID 29383146, 2017). "EphA3 upregulation in small-cell lung cancer (SCLC) lowered therapeutic resistance by promoting apoptosis and triggering G0/G1 arrest, which was associated with decreased phosphorylation of the PI3K/BMX/STAT3 signalling." (PMID 36830852, 2023).
astrocytoma (3 papers, 2016 to 2024). "Within the IDH mutant astrocytoma and oligodendroglioma groups, EPHA3 and NPAP1 surfaced as recurring genes potentially connected to the upregulation of INTS9." (PMID 37537630, 2023). "EphA3 was also present in all 4 anaplastic oligodendrogliomas examined (WHO grade II/III) and less so in meningiomas and lower grade astrocytomas (WHO grade II)." (PMID 27494882, 2016).
clear-cell renal cell carcinoma (3 papers, 2019 to 2022). "And yet, the downregulation of EphA3 protein is detected in clear-cell renal cell carcinoma and negatively associated with tumor diameter and advanced stage of patients." (PMID 36578556, 2022). "Moreover, a previous study highlighted the association of deletion of EPHA3 protein expression with advanced tumor-node-metastasis (TNM) in clear renal cell carcinoma." (PMID 31262977, 2019).
lung adenocarcinoma (3 papers, 2014 to 2022). A carcinoma that arises from the lung and is characterized by the presence of malignant glandular epithelial cells. "The EPH receptor A3 (EPHA3) tyrosine kinase is among the most frequently mutated cancer genes in human lung adenocarcinomas." (PMID 25713296, 2015). "Several mutations in Eph family members, including EphA3, A5, A7, B1 and B6 were identified in lung adenocarcinoma, while advanced stage tumours presented accumulated more EphA7 mutations compared to low stage tumours." (PMID 24495444, 2014).
bladder cancer (2 papers, 2023 to 2025). "Nevertheless, the relevance of EPHA3 with a progression to bladder cancer and the patient’s clinicopathological characteristics have not been reported, which deserve further exploration." (PMID 36765579, 2023).
brain cancer (2 papers, 2024 to 2025). A primary or metastatic malignant neoplasm affecting the brain. "EphA3 is a potential therapeutic target, especially in hematopoietic malignancies and brain cancers." (PMID 40688499, 2025).
colorectal tumors (2 papers, 2006 to 2017). "In colorectal tumors, the mutations observed in EPHA3 have been shown to disrupt its ligand binding capacity or its kinase activity." (PMID 28169277, 2017). "We next investigated whether the EPHA3 mutations frequently observed in colorectal tumors are oncogenic." (PMID 28169277, 2017). "Also somatic mutations in the kinase domain of EPHA3 have been identified in colorectal tumors." (PMID 16740153, 2006). "Collectively, our results indicate that wild type EPHA3 does not regulate the growth or metastasis of colorectal tumors." (PMID 28169277, 2017). "Collectively, our results indicate that EPHA3 inactivation is not an important step in the tumorigenic process of colorectal tumors, and highlights the need to functionally validate the findings of large exome/genome sequencing studies." (PMID 28169277, 2017).
head and neck cancer (2 papers, 2020 to 2021). A primary or metastatic malignant neoplasm affecting the head and neck. "We demonstrated previously that EPHA3 is associated with radiation resistance in head and neck cancer via the PTEN/Akt/EMT pathway; the inhibition of EPHA3 significantly enhances the efficacy of radiotherapy in vitro and in vivo." (PMID 33919657, 2021). "Our results suggest that EPHA3 could display a novel regulatory mechanism for the epigenetic regulation of PTEN in radioresistant head and neck cancer cells." (PMID 33919657, 2021).
intestinal tumor (2 papers, 2017 to 2022). "In good agreement with this finding, the number, size or histological type of intestinal tumors at 41 weeks of age was not different in Apcmin/+ mice that are either wild type, heterozygous or homozygous for the EphA3 knockout allele." (PMID 28169277, 2017). "Overall, these experiments indicate that, unlike the loss of EphB receptors, EphA3 inactivation does not significantly contribute to intestinal tumor initiation or progression during the early stages of the tumorigenic process in murine models." (PMID 28169277, 2017). "Importantly, we found that the loss of Epha3 does not affect adult animal survival or the incidence of intestinal tumors at 20 months of age, indicating that the loss of Epha3 does not promote tumor initiation." (PMID 28169277, 2017). "Analogously, the upregulation and the downregulation of mutant EPHA3 expression did not exhibit any impact on cell growth and motility, while silencing of EPHA3 neither triggered carcinogenesis nor altered the tumor size of established intestinal tumors." (PMID 35269901, 2022).
liver cancer (2 papers, 2017 to 2024). An epithelial or non-epithelial malignant neoplasm that arises from the liver. "In human liver cancer, VIM-AS1 was found to be downregulated, leading to increased tumor aggressiveness, including the migration and invasion of tumor cells, through the regulation of EPHA3 mRNA stability." (PMID 39617786, 2024).
lymph node metastasis (2 papers, 2017 to 2020). "High expression of EphA3 was associated with differentiated histology (p < 0.001), depth of tumor (p = 0.002), lymph node metastasis (p = 0.001), stage (p < 0.001), recurrence (p = 0.024), especially liver recurrence (p = 0.024) and HER2 expression (p = 0.017)." (PMID 28465671, 2017). "Other factors like FAT3, APC, PTPRD (P = 0.01), lymph-node metastasis, EPHA3, TERT, and STK11 (P = 0.05) that have been found to be related to TMB distribution." (PMID 33996530, 2020).
medulloblastoma (2 papers, 2022 to 2024). A malignant, invasive embryonal neoplasm arising from the cerebellum. "Having detected cell surface expression of EphA3 on primary tumors and cell lines in pediatric DMG and medulloblastoma, we next sought to determine if targeting EphA3 was applicable to other pediatric CNS tumors." (PMID 39111833, 2024). "These could target the defective DNA damage repair in the LFS-associated medulloblastoma, the prolactin autocrine loop in the atypical prolactinoma, the EPHA3/7 and ALK overexpression in the FAP-associated medulloblastoma, and the multi-RTK upregulation in the soft tissue neoplasms." (PMID 35978432, 2022).
meningioma (2 papers, 2016). A generally slow growing tumor attached to the dura mater. "Autosomal genes that were comparably lower expressed in meningiomas from females included EPH receptor A3 (EPHA3), parvalbumin (PVALB), calbindin 2 (CALB2), and solute carrier family 38 member 3 (SLC38A3)." (PMID 27096627, 2016).
Obesity (2 papers, 2017 to 2022). Accumulation of substantial excess body fat. "In the current study, we hypothesized that the deletion of hypothalamic EphA3 might cause disturbances of hypothalamic neuron function, leading to the disruption of energy balance and the development of obesity." (PMID 37013864, 2022). "Our results showed that the hypothalamic EphA3 knock-out mice exhibited a more severe obesity phenotype under the high-fat diet feeding." (PMID 37013864, 2022). "Together, these results indicated that the deletion of EphA3 in the hypothalamus promoted hyperphagia and obesity in the DIO mice." (PMID 37013864, 2022). "Recently, we have found that the expression of EphA3 is elevated in the hypothalamus of mice with diet-induced obesity (DIO)." (PMID 37013864, 2022). "The results showed that the expression of EphA3 in both mRNA and protein levels increased in the hypothalamus of obesity mice." (PMID 37013864, 2022). "By adeno-associated virus (AAV)-mediated CRISPR-Cas9 gene editing technology, we knocked out the expression of EphA3 in the hypothalamus and found that these mice displayed severe obesity phenotype under high-fat diet feeding." (PMID 37013864, 2022). "However, under the high-fat diet feeding, the hypothalamic EphA3 knock-out mice exhibited a more severe obesity phenotype than control mice." (PMID 37013864, 2022). "The hypothalamic EphA3 knock-out mice showed significant weight gain and rapid obesity development." (PMID 37013864, 2022). "Therefore, whether EphA3, as one of the tyrosine kinase receptors, also has a similar resistance mechanism in obesity development remains to be determined." (PMID 37013864, 2022). "Therefore, we speculated that hypothalamic EphA3 might play a protective role in preventing obesity, which may share some similarities with leptin resistance in the hypothalamus of obese mice." (PMID 37013864, 2022). "Recently, we have found that the expression of EphA3 is elevated in the whole hypothalamus of diet-induced obesity (DIO) mice (data not yet published)." (PMID 37013864, 2022). "In the current study, we demonstrated that the deletion of EphA3 in the hypothalamus by CRISPR/Cas9-mediated gene editing promotes obesity in male mice with high-fat diet feeding rather than those with normal chow diet feeding." (PMID 37013864, 2022).
renal carcinoma (2 papers, 2011 to 2024). A carcinoma arising from the epithelium of the renal parenchyma or the renal pelvis. "This revelation suggested that EphA3 may play a regulatory role as an immunomodulator in the renal cancer microenvironment." (PMID 38952552, 2024). "These insights further accentuate the alignment of EphA3 expression with immune infiltration in KIRP, validating its role as a modulator of immune evasion within the renal cancer microenvironment." (PMID 38952552, 2024).
sarcoma (2 papers, 2022). A usually aggressive malignant neoplasm of the soft tissue or bone. "Thus, ephrin-A5 could have been investigated as a potential tumor-suppressing ligand through the interaction with its tumor promoting receptors such as EPHA2, EPHA3, EPHA4, EPHA5, EPHA7, EPHA8, and EPHB2 in sarcomas." (PMID 35563562, 2022).
breast tumours (1 paper, 2023). "We used a single-cell RNA sequencing analysis of 26 early-stage breast tumours to analyse EphA3 expression in distinct cell types based on gene expression profiles." (PMID 37760615, 2023). "Interestingly, we also tested EphA3 expression in a human breast fibroblast cell line that had been ‘tumour-educated’ by co-implantation with human breast tumour cells in a mouse xenograft model, inducing a myofibroblast-like CAF phenotype." (PMID 37760615, 2023). "Our data from early-stage breast tumours shows that EphA3 is particularly expressed in stromal CAF populations that express genes typical of myofibroblast-like perivascular/smooth muscle cells, including SMA, Transgelin, and other genes associated with acto-myosin regulation." (PMID 37760615, 2023).
cardiac failure (1 paper, 2016). "Interestingly, Epha3-null embryos are perinatal lethals with ASD and cardiac failure, and have earlier atrioventricular cushion defects." (PMID 27518902, 2016).